ACOT1 (acyl-CoA thioesterase 1)
Description:
Catalyzes the hydrolysis of acyl-CoAs into free fatty acids and coenzyme A (CoASH), regulating their respective intracellular levels. More active towards saturated and unsaturated long chain fatty acyl-CoAs (C12-C20).
Synonyms: ACH2; CTE-1; LACH2
Tractability: PROTAC: ubiquitination databases record sites on it; its protein half-life has been measured.
Target class: Enzyme; Hydrolase
Gene: Protein-coding gene on chromosome 14 (73,537,143 to 73,543,796, forward strand). Ensembl gene ENSG00000184227.
Subcellular location: Cytoplasm, cytosol
Subcellular location (Human Protein Atlas): Mitochondria
Pathways (Reactome):
Metabolism: Mitochondrial Fatty Acid Beta-Oxidation
Gene Ontology:
Molecular function: fatty acyl-CoA hydrolase activity; protein binding; long-chain fatty acyl-CoA hydrolase activity; medium-chain fatty acyl-CoA hydrolase activity; thiolester hydrolase activity
Biological process: acyl-CoA metabolic process; long-chain fatty acid metabolic process; very long-chain fatty acid metabolic process; fatty acid metabolic process; lipid metabolic process; monocarboxylic acid metabolic process
Cellular component: cytosol; mitochondrion; peroxisome
Genetic constraint (gnomAD): Loss-of-function variants: 2 observed, 3.86 expected, observed/expected ratio (o/e) 0.52, 90% interval 0.21 to 1.53. That is too few expected variants to judge how well the gene tolerates losing a copy. Missense variants: 56 observed, 159.52 expected, observed/expected ratio (o/e) 0.35, 90% interval 0.28 to 0.44. Synonymous variants: 18 observed, 64.5 expected, observed/expected ratio (o/e) 0.28, 90% interval 0.19 to 0.41.
Homologues: Orthologues: rat Acot3 (77% identical), mouse Acot3 (77% identical), rat Acot1 (77% identical), mouse Acot1 (76% identical), mouse Acot2 (76% identical), rat Acot2 (75% identical), mouse Acot5 (74% identical), rat Acot5 (74% identical), rat Acot5 (68% identical), tropical clawed frog acot2 (59% identical), tropical clawed frog jmjd7 (49% identical), zebrafish acot20 (46% identical), and 6 more. Paralogues in human: ACOT2 (99% identical), ACOT4 (70% identical), ACOT6 (69% identical), BAAT (45% identical).
Diseases named in the same sentence as ACOT1 in open-access papers:
ACOT1 is named in the same sentence as 39 diseases in open-access papers, as found by Europe PMC text mining. Sharing a sentence is not in itself a finding about the gene and the disease. The quoted sentences say what the papers report.
cardiomyopathy (6 papers, 2012 to 2023). A disease of the heart muscle or myocardium proper. "Under the condition of doxorubicin-induced cardiomyopathy, Acot1 knockdown sensitizes CMs to ferroptosis, whereas ACOT1 overexpression poses defensive effect on cellular ferroptosis." (PMID 36003910, 2022). "Our previous studies have reported that Acot1 overexpression prevents cardiac dysfunction in both LPS-induced cardiomyopathy and diabetic cardiomyopathy by reducing oxidative stress." (PMID 32934217, 2020). "Since enhanced FAs β-oxidation, following the oversupply of long-chain acyl-CoAs in diabetic hearts is attributable to initiation of oxidative stress and finally cardiomyopathy, the hydrolyzation of long-chain acyl-CoAs by ACOT1 is predicted to be an effective inhibition of increased FAs oxidation." (PMID 23226270, 2012). "Moreover, our previous studies have figured out that Acot1 may cast a cardioprotective effect in the process of LPS-induced cardiomyopathy and diabetic cardiomyopathy by decreasing the oxidative stress in cardiomyocytes." (PMID 32934217, 2020). "Conversely, knockdown of MITOL/MARCH5 aggravated DIC, and this aggravation of cardiomyopathy could be offset by fer-1 In addition to GPX4, acyl-coenzyme A thioesterase 1 (Acot1) is also involved in lipid metabolism, that inhibit lipid peroxidation." (PMID 36918950, 2023). "Moreover, the authors found that acyl-CoA thioesterase 1 (Acot1), one of the leading-edge core genes, protects the deterioration of DOX-induced cardiomyopathy by suppressing ferroptosis." (PMID 34368260, 2021).
diabetes (4 papers, 2012 to 2024). "Consistently, ACOT1 deficiency had opposite effects, which accelerated the cardiac damage induced by diabetes." (PMID 23226270, 2012). "Consistently, ACOT1 deficiency showed opposite effects, which accelerated the cardiac damage induced by diabetes." (PMID 23226270, 2012). "Using Millar cardiac catheter system, we found that ACOT1 overexpression alleviated cardiac dysfunction of diabetes, while deterioration of cardiac deficits was observed when ACOT1 was downregulated by siRNA delivery system." (PMID 23226270, 2012). "Similarly, one study showed that, when the body contained higher fatty acids, as a result of diabetes or a high-fat diet, the expression of Acot1 and Acot2 was upregulated in liver, thereby promoting the catabolism of fatty acids." (PMID 27798284, 2016). "Similarly to our present findings, gene expression of cytosolic acyl-CoA thioesterase 1 has been reported to be up-regulated by high fat diet or STZ-induced diabetes in the rat myocardium." (PMID 23320804, 2013). "Therefore, both hemodynamic and echocardiographic detection of improved cardiac function reflect the recovery of cardiac efficiency in diabetes by overexpression of ACOT1." (PMID 23226270, 2012). "In this study, we have shown that diabetes resulted in enhanced cardiac expression of ACOT1." (PMID 23226270, 2012). "Hence, it was possible that, through the attenuation of enhanced FAO, overexpression of ACOT1 reversed diabetes-induced altered myocardial energy substrate use to ameliorate cardiac dysfunction." (PMID 23226270, 2012). "We also investigated whether and how ACOT1 affected cardiac function in diabetes via negative feedback of activated FAs oxidation." (PMID 23226270, 2012). "Furthermore, diabetes upregulates lysophosphatidylcholine acyltransferase-3 (LPCAT3), facilitating the integration of polyunsaturated fatty acids (PUFA) into phospholipid membranes, and downregulates acyl-CoA thioesterase-1 (ACOT1), which further promotes ferroptosis." (PMID 38824159, 2024).
gastric cancer (4 papers, 2022 to 2025). A primary or metastatic malignant neoplasm involving the stomach. "ACOT1, a gene for intracellular energy metabolism, could significantly promote the formation of gastric cancer tumor tissues and is associated with poor prognosis of gastric cancer." (PMID 36348469, 2022). "To further clarify the mechanistic role of ACOT1 in piperine's anti-cancer effects, we conducted the comprehensive functional validation experiments using shRNA technology to knock down ACOT1 expression in gastric cancer cells." (PMID 40855327, 2025). "Second, the identification of ACOT1 as a novel therapeutic target in gastric cancer expands the repertoire of potential interventions beyond conventional cytotoxic approaches." (PMID 40855327, 2025). "recently found that ACOT1 was abnormally overexpressed in gastric cancer tissues, which significantly correlated with a poor prognosis of gastric cancer patients." (PMID 35785165, 2022). "ACOT1, an acyl-CoA thioesterase that regulates fatty acid metabolism by hydrolyzing acyl-CoAs to free fatty acids and CoA, emerged as a significant prognostic factor in gastric cancer from our TCGA analysis." (PMID 40855327, 2025). "In conclusion, our comprehensive investigation establishes that Piper Longum exerts potent anti-gastric cancer effects through a multi-modal mechanism involving metabolic reprogramming and gut microbiota modulation, with ACOT1 serving as a central molecular target." (PMID 40855327, 2025). "Our integrated analysis revealed that Piper Longum exerts potent anti-gastric cancer effects by reprogramming lipid metabolism pathways and modulating gut microbiota composition, with Acyl-CoA Thioesterase 1 (ACOT1) serving as a critical molecular target of piperine." (PMID 40855327, 2025). "Four distributed genes ACOT1, GSTM1, SIGLEC14, and UGT2B17 showed extremely high frequencies of absence in the gastric cancer population." (PMID 36109518, 2022). "Genes ACOT1, GSTM1, SIGLEC14, and UGT2B17 are highly absent in Chinese Hans, even in the Asian population, compared to the non-Asian healthy population, suggesting a potential association for the high incidence of gastric cancer in the Asian population." (PMID 36109518, 2022). "Genes ACOT1, GSTM1, SIGLEC14 and UGT2B17 are identified as highly absent genes in gastric cancer population." (PMID 36109518, 2022).
Hepatic steatosis (4 papers, 2008 to 2024). Steatosis is a term used to denote lipid accumulation within hepatocytes. "Increased ACOT1 resulted in de novo lipogenesis with increased macrovesicular hepatic steatosis, along with a gene expression profile compatible with hepatic steatosis and damage." (PMID 39624175, 2024). "Of those commonly upregulated, Acox1, Acot1, and Acot2 are all involved in lipid catabolism, lipid synthesis, liver inflammation, and hepatic steatosis." (PMID 38787127, 2024). "The downregulation of Acot1 likely leads to increased Acyl-CoA and subsequent beta oxidation, which might counter-regulate hepatic steatosis secondary to HCV core expression." (PMID 18307821, 2008).
steatosis (4 papers, 2019 to 2025). Increased lipid within the cytoplasm of cells. "The Acot1 is a cytoplasmic thioesterase that converts acyl coenzyme A to fatty acids and CoA, and is a central node in the interactome of the transition from steatosis to MASH (metabolic dysfunction-associated steatohepatitis)." (PMID 40650265, 2025). "ACOT1 mRNA abundance was significantly greater in MASH patients (ACOT1 mean value = 11.21 ± SD 2.16) as compared to steatosis only (ACOT1 mean value = 9.40 ± SD 2.16) with a fold change of 2.99." (PMID 39624175, 2024). "Histological examination of the liver revealed evidence of ballooning, hypertrophy, and a higher grade (grade 3) of macrovesicular steatosis in the ACOT1-overexpressing mice compared to the control group." (PMID 39624175, 2024). "Acyl-CoA thioesterase 1 (ACOT1) was identified as a critical node in the protein-protein interaction (PPI) network of the transition from steatosis to MASH in patient samples." (PMID 39624175, 2024). "ACOT1 expression was 3-fold higher in MASH as compared to steatosis." (PMID 39624175, 2024). "Thus, when a high fat diet induces steatosis, ACOT1 protects against inflammation and oxidative stress that lead to fibrosis." (PMID 33853536, 2021). "Conversely, upregulation of ACOT1 via an adenoviral vector resulted in development of MASH, whereas control mice only developed steatosis." (PMID 39624175, 2024). "Upregulation of ACOT1 resulted in MASH via increased accumulation of glycerophospholipids, as compared to steatosis only in control mice." (PMID 39624175, 2024). "ACOT1-mRNA level was confirmed as significantly decreased in the animals injected with the shRNA-ACOT1 adenovirus compared to the scramble vector by microarray and was accompanied by a notable decrease in the serum ALT and a significant decrease in steatosis (p = 0.02)." (PMID 39624175, 2024). "Using this approach, we identified acyl-CoA thioesterase 1 (ACOT1), a cytoplasmic thioesterase that converts acyl-CoAs to fatty acids and CoA, as being a central node in the interactome of the transition from steatosis to MASH, with a 3-fold higher expression in MASH patients compared to steatosis." (PMID 39624175, 2024).
diabetic cardiomyopathy (3 papers, 2012 to 2026). Diabetic cardiomyopathy is a disorder of the heart muscle in people with diabetes. "This could be another mechanism to explain why overexpression of ACOT1 could reverse metabolic substrate alteration and protect against diabetic cardiomyopathy." (PMID 23226270, 2012).
Insulin resistance (3 papers, 2012 to 2023). Increased resistance towards insulin, that is, diminished effectiveness of insulin in reducing blood glucose levels. "Serpine 1, an adipokine in thrombosis and insulin resistance regulation, was substantially upregulated, and genes involved in lipid metabolism, including Slc27a2, Acsm3, Acot1, and Ucp3, were dramatically decreased in BAT of BMRKO-HFD mice." (PMID 37734559, 2023). "HP/HI induced insulin resistance and lipid storage was accompanied by increased Cd36, Acot1, and Ucp3 mRNA levels." (PMID 26649034, 2015). "Taken together, we see from its enzymatic function that ACOT1 reduced the overload of long-chain acyl-CoAs, the accumulation of which has been proven to promote the development of insulin resistance and cellular apoptosis." (PMID 23226270, 2012).
metabolic syndrome (3 papers, 2006 to 2016). A cluster of metabolic risk factors for CARDIOVASCULAR DISEASES and TYPE 2 DIABETES MELLITUS. "The increased expression of stearoyl-CoA desaturase-1 (SCD-1) plays a key role in lipogenic gene expression and in metabolic syndrome, which coincides with marked elevations of lipoprotein lipase (Lpl, 33-fold) and cytosolic acyl-CoA thioesterase-1 (Cte1, 5-fold) in arsenic-induced HCC." (PMID 16507464, 2006).
Obesity (3 papers, 2016 to 2024). Accumulation of substantial excess body fat. "HFD and obesity or type 2 diabetes are associated with upregulated ACOT1 abundance, suggesting ACOT1 may have a role in the development of obesity and, thus, may be a potential therapeutic target." (PMID 37561578, 2023). "In conclusion, the data presented in the current study suggest that ACOT1 inhibition attenuates BW gain during diet-induced obesity by increasing energy expenditure through UCP2 in hepatocytes." (PMID 37561578, 2023). "Together, these data indicate that targeting ACOT1 may be effective for obesity prevention during caloric excess by increasing energy expenditure." (PMID 37561578, 2023). "Nevertheless, pharmacological agents that inhibit ACOT1 may have clinical utility in preventing or treating obesity or diseases with alterations in lipid metabolism." (PMID 37561578, 2023). "Acyl-CoA thioesterase 1 (ACOT1) catalyzes the hydrolysis of long-chain acyl-CoAs to free fatty acids and CoA and is typically upregulated in obesity." (PMID 37561578, 2023). "They showed that some lipid metabolism-related genes (i.e., Mod1, Cyp4a10, Hmgcs2, Acot1, Acot2, Pdk4, Acaa1b, Cpt1, Fabp1, and Acadl) were significantly up-regulated in the intestine of both A/J (obesity-resistant) and C57BL/6J (obesity-prone) mice fed with high fat diet." (PMID 26861690, 2016). "Whether targeting ACOT1 in the setting of high-fat diet–induced (HFD-induced) obesity would be metabolically beneficial is not known." (PMID 37561578, 2023).
gastric adenocarcinoma (2 papers, 2020 to 2022). "It was shown that an increased expression of ACOT1 was correlated with pivotal clinicopathological parameters and poor prognosis in gastric adenocarcinoma." (PMID 36230586, 2022). "High expression of ACOT1 is related to unfavorable prognosis of gastric adenocarcinoma via increased tumor-promoting protein GLI3, while ACOT8 is demonstrated to be an independent predictor of lymph node metastasis and survival of lung adenocarcinoma." (PMID 33362855, 2020).
heart failure (2 papers, 2022 to 2024). Inability of the heart to pump blood at an adequate rate to meet tissue metabolic requirements. "Our results suggest that COMP, COL8A1, LOX, and ACOT1 warrant further investigation in the development of cardiac fibrosis and as potential biomarkers for causing heart failure." (PMID 38854759, 2024). "Overexpression of lysine-specific demethylase 3A (KDM3A) leads to the up regulation of fibrosis-related genes COMP, COL8A1, and LOX and the down regulation of ACOT1, result in enhanced fibrosis and heart failure." (PMID 38854759, 2024).
type 2 diabetes (2 papers, 2012 to 2023). "A recent study using an ATAC-Seq analysis found that hepatic ACOT1 is elevated and deregulated in individuals with type 2 diabetes." (PMID 37561578, 2023). "Here, we studied the role of ACOT1 in myocardia of db/db mice, an animal model of type 2 diabetes, compared with normal control C57BL/Ks." (PMID 23226270, 2012). "In the present study, we found that ACOT1 was upregulated in the myocardial tissue of db/db mice, an animal model of type 2 diabetes." (PMID 23226270, 2012).
Cachexia (1 paper, 2021). Severe weight loss, wasting of muscle, loss of appetite, and general debility related to a chronic disease. "Consistently, the loss of epididymal adipose tissues in cachexia mice was accompanied by upregulated expressions of fatty acid translocase CD36 and Acyl-coenzyme A thioesterase 1 (Acot1) in the CAC gastrocnemius, which facilitated mobilization and oxidation of adipose tissues." (PMID 34229732, 2021).
clear cell renal cell carcinoma (1 paper, 2023). "In clear cell renal cell carcinoma (ccRCC), the majority of ACOT members, including ACOT1, ACOT2, ACOT3, ACOT8 and ACOT11, are downregulated in the cancer samples." (PMID 37003979, 2023).
Hepatic fibrosis (1 paper, 2024). The presence of excessive fibrous connective tissue in the liver. "Our animal experiment was limited by cessation of the experiment prior to development of hepatic fibrosis, and we therefore could not evaluate the effect of ACOT1 overexpression on development of fibrosis." (PMID 39624175, 2024).
hypertrophy (1 paper, 2012). Hypertrophy is the increase in the volume of an organ or tissue due to the enlargement of its component cells. "Overexpression of ACOT1 attenuated these LVH indicators as well as whole heart weight and ratio of heart/body weight which represents hypertrophy at the overall level, suggesting a protective role of ACOT1." (PMID 23226270, 2012).
left ventricular hypertrophy (1 paper, 2012). Enlargement of the LEFT VENTRICLE of the heart. "Consistent with this in vivo cardiac function analysis using the pressure-volume relationship, the echocardiographic assessment showed that overexpressed ACOT1 induced moderation of left ventricular hypertrophy (LVH) compared with untreated db/db mice." (PMID 23226270, 2012).
lipid metabolic disorders (1 paper, 2025). "ACOT1, ACOT4, and ACOT6 are acyl-CoA thioesterases that catalyze the hydrolysis of acyl-CoA into FFAs and CoASH, playing key roles in fatty acid metabolism, and their regulation may help alleviate lipid metabolic disorders." (PMID 41194880, 2025).
lung carcinoma (1 paper, 2017). "In contrast, TSG101, involved in lung cancer cell proliferation, RAB34, HYOU1 and ACOT1 showed higher expression in AC, as compared to their levels in SCC." (PMID 29285267, 2017).
nonalcoholic fatty liver disease (1 paper, 2024). "In patient samples, ACOT1 was significantly correlated with the severity of MASH as reflected by the nonalcoholic fatty liver disease score." (PMID 39624175, 2024).
nonalcoholic steatohepatitis (1 paper, 2020). "Three genes in particular, ACOT1, ADIPOR2 and ADORA1, are associated with nonalcoholic steatohepatitis." (PMID 32075112, 2020).
Pitt-Hopkins-like syndrome 2 (1 paper, 2017). Any Pitt-Hopkins-like syndrome in which the cause of the disease is a mutation in the NRXN1 gene. "NRXN3 encodes a member of the neurexin family of which NRXN1 is associated with Pitt-Hopkins-like syndrome 2 (MIM 614325) and ACOT1 is involved in lipid metabolism." (PMID 28327206, 2017).
Sepsis (1 paper, 2025). Sepsis is defined as life-threatening organ dysfunction caused by a dysregulated host response to infection. "Remarkably, gene expression of the fatty-acyl-CoA inactivating enzyme acyl-CoA thiosterase 1 (Acot1) was significantly increased in acute sepsis (d1), and remained elevated during prolonged sepsis, although to a lesser extent." (PMID 39821755, 2025).